ZEB2 (zinc finger E-box binding homeobox 2)
Diseases named in the same sentence as ZEB2 in open-access papers (continued):
Sharing a sentence is not in itself a finding about the gene and the disease.
kidney failure (1 paper, 2023). An acute or chronic condition that is characterized by the inability of the kidneys to adequately filter the blood. "Interestingly, we did not observe any glomerular cystic phenotype in stromal cell–specific Zeb2-cKO mice (Zeb2fl/fl;Foxd1-Cre+), suggesting a different underlying cause for kidney failure and early mortality in these mice." (PMID 36445780, 2023). "Loss of Zeb2 in FOXD1+ stromal progenitors leads to kidney failure and early mortality." (PMID 36445780, 2023). "Zeb2-deficient FOXD1+ stromal progenitors also took on a myofibroblast fate that led to kidney fibrosis and kidney failure." (PMID 36445780, 2023). "Taken together, these findings indicate that loss of Zeb2 in FOXD1+ stromal progenitors causes kidney fibrosis and kidney failure." (PMID 36445780, 2023). "In the absence of ZEB2, FOXD1+ stromal progenitors fail to differentiate into mature stromal cells such as pericytes and resident fibroblasts supporting normal kidney development and instead become myofibroblasts, leading to hypoplastic kidney, kidney fibrosis, and kidney failure." (PMID 36445780, 2023).
Listeria monocytogenes infections (1 paper, 2025). "Zeb2 encodes a transcription repressor that promotes the expansion and terminal differentiation of effector T cells in lymphocytic choriomeningitis virus and Listeria monocytogenes infections." (PMID 40396260, 2025).
lung tumor (1 paper, 2018). "Furthermore, expression levels of the downstream markers of the corresponding microRNAs, namely PTEN, MARCKs, TPM-1, PDCD4, SPRY-2, ETS-1, ZEB-2, FGFRL-1, EFNA-3, and k-RAS were downregulated in the lung tumor lesions of patients with the underlying condition compared to non-COPD patients." (PMID 29371906, 2018).
malaria (1 paper, 2023). Malaria is a serious and sometimes fatal disease caused by a parasite that commonly infects a certain type of mosquito which feeds on humans. "We compared the frequency of ZEB2+ memory CD4+ T cells during the enrollment episode of clinical malaria to the frequency during a subsequent episode of clinical malaria between the two groups." (PMID 38001069, 2023). "More than 95% of the expanded clones sharing identical TCR clonotypes in protected participants during a malaria illness, expressed a robust TH1 cytolytic effector program including transcripts encoding for multiple lytic effector proteins and the TFs ZEB2, T-BET, and RUNX3 (cluster 1)." (PMID 38001069, 2023). "Since ZEB2+ memory CD4+ T cells contained clonally expanded P. falciparum CSP-specific T cells, we next hypothesized that protected patients should have greater proportion of these cells than susceptible ones, if these cells are indeed associated with clinical immunity against malaria." (PMID 38001069, 2023). "Given the importance of TF in orchestrating T cell fates, we focused on the ZEB2 TF and first confirmed that we could detect a population of ZEB2+ memory CD4+ T cells in PBMC from malaria-infected patients by flow cytometry." (PMID 38001069, 2023). "The ZEB2+ memory CD4+ T cells in these two groups expanded only in the blood of those gaining clinical immunity but not in the other group, consistent with our original hypothesis that expansion of these cells may correlate with the acquisition of protective immunity against clinical malaria." (PMID 38001069, 2023). "Importantly, we reveal in malaria-infected participants the existence of a population of clonally expanded memory CD4+ T cells that share identical TCR clonotypes and express a robust cytolytic signature and the ZEB2 master regulator of terminally differentiated effector cells." (PMID 38001069, 2023).
MALT lymphoma (1 paper, 2022). An indolent, extranodal type of non-Hodgkin lymphoma composed of small B-lymphocytes (centrocyte-like cells). "In the miR-383/ZEB2 pathway, low expression of miR-383 caused the upregulation of ZEB2 in gastric MALT lymphoma tissue and cells." (PMID 36313570, 2022). "In gastric MALT lymphoma tissues, a negative association was also found between the expression levels of miR-383 and ZEB2." (PMID 36313570, 2022).
Marfan syndrome (1 paper, 2017). A disorder of the connective tissue. "Many genes encoding collagen, Timps and other proteins known to be involved in connective tissue diseases such as EDS and Marfan syndrome, including Adamts2, Fbn1 and Fbn2, had more than a 4-fold decreased expression in Zeb2-cKO fibroblasts compared with wild-type fibroblasts." (PMID 28422173, 2017).
medulloblastoma (1 paper, 2015). A malignant, invasive embryonal neoplasm arising from the cerebellum. "Next, we transfected the medulloblastoma cells with miR-192 and analyzed EMT-related genes and proteins such as ZEB2, E-cadherin and VIM after miR-192 transfection." (PMID 26506238, 2015). "ZEB2 mRNA and protein expression were not stimulated by the overexpression of miR-192 in any of the medulloblastoma cell lines." (PMID 26506238, 2015). "Although VIM was reduced by miR-192 transfection in all medulloblastoma cells, EMT-related proteins such as ZEB2 and E-cadherin were not affected." (PMID 26506238, 2015).
mycoplasma infection (1 paper, 2017). "Twist and Zeb2 mRNA were not detectable in Isreco1(+/− Co-029) cells, whereas there was a generally moderate increase of Snail and Slug when cells were plated on collagen but independently of mycoplasma infection." (PMID 28418857, 2017).
neural tube defect (1 paper, 2023). A congenital defect characterized by failure of the neural tube to close completely; this results in the presence of openings in the brain or spinal cord. "As ExomiR-251-5p acts as a downstream regulator of ZEB2, it increases the proangiogenic effect leading to the ExomiR causing Neural Tube Defects (NTD)." (PMID 36843574, 2023).
ovarian adenocarcinoma (1 paper, 2015). An adenocarcinoma that arises from the ovary. "Our findings demonstrated that ZEB2 knock-down in Hey ovarian adenocarcinoma cells impaired migration, invasion and anchorage-independent cell growth, indicating a pivotal role for ZEB2 in progression of ovarian carcinogenesis." (PMID 26136338, 2015).
ovarian epithelial tumor (1 paper, 2017). A benign, borderline, or malignant tumor that originates from the surface epithelium of the ovary. "Ovarian epithelial tumor cells showed concurrent up-regulation of miR-200, down-regulation of the four target genes (ZEB1, ZEB2, TGFβ1 and TGFβ2), and up-regulation of effector genes that were negatively regulated by the target genes." (PMID 28623900, 2017).
ovarian serous cystadenocarcinoma (1 paper, 2022). A malignant serous cystic epithelial neoplasm arising from the ovary. "The positive correlation between HK2 and CDH2, fibronectin, MMP9, ZEB1, ZEB2 and vimentin in OV (ovarian serous cystadenocarcinoma) was confirmed by using TIMER 2.0." (PMID 35953860, 2022).
papilloma (1 paper, 2015). A benign epithelial neoplasm that projects above the surrounding epithelial surface and consists of villous or arborescent outgrowths of fibrovascular stroma. "We validated by qRT-PCR the upregulation of EMT drivers, such as Zeb1, Zeb2, Twist and Prrx1, and EMT mediators, such as Wnt5a, Vcan, Ncadh and Mmp2 both in Nanog-papillomas and in Nanog-SCCs." (PMID 25988972, 2015). "In particular, Nanog-overexpressing papillomas show upregulation of several EMT mediators (Zeb1, Zeb2, Twist) and the master EMT inducer Prrx1, but not of the classical EMT inducers Snail/Slug." (PMID 25988972, 2015).
peritoneal (1 paper, 2020). "Moreover, consistent with the promotion of EMT by CAFs-derived IL-33 in vitro, there were also decreased expression of ZEB2 in peritoneal tumors derived from GC cells mixed with CAFs-siRNA/IL-33 than in tumors derived from GC cells mixed with CAFs-siRNA/NC." (PMID 31659258, 2020).
pharyngeal diseases (1 paper, 2023). "Similarly, the GWS CDTA-associated loci 1p36.23 and 16p11.2 were MTS associated with pharyngeal diseases, and the NP-associated locus 2q22.3 near ZEB2 was MTS associated with sinonasal diseases." (PMID 36653354, 2023).
Pleural effusion (1 paper, 2025). The presence of an excessive amount of fluid in the pleural cavity. "Analysis of DEGs in Cycling GZMA and GZMA CD4 T cells from pleural effusion of HP and LCP revealed that seven transcription factors (MLLT3, KLF12, FOXP1, NFKB1, ZEB2, TOX, JAZF1) were upregulated in both cycling GZMA CD4 and GZMA CD4 cells in MPE of LCP." (PMID 40959273, 2025).
rectal cancer (1 paper, 2018). A primary or metastatic malignant neoplasm that affects the rectum. "ZEB2 expression was an independent biomarker in all cases, including patients with node-negative and rectal cancer." (PMID 30646224, 2018).
sarcoidosis (1 paper, 2025). Sarcoidosis is a multisystemic disorder of unknown cause characterized by the formation of immune granulomas in involved organs. "By contrast, T cells from sarcoidosis patients exhibited clonal expansion of terminally differentiated CD8+ effectors that expressed high levels of effector genes, including CCL5, GZMB, PRF1, IFNG, KLRG1 and ZEB2." (PMID 40469525, 2025).
Sepsis (1 paper, 2022). Sepsis is defined as life-threatening organ dysfunction caused by a dysregulated host response to infection. "However, only a small part of MVPs have relatively large Δβ (|Δβ|> 0.2), and focusing on those with large Δβ, we found that 6 of 26 differentially methylated genes (23.1%) were previously associated with sepsis in the literature, including ALK, ZEB2, MNDA, AIM2, TLR5, and JUNB." (PMID 35242787, 2022).
steatosis (1 paper, 2025). Increased lipid within the cytoplasm of cells. "Endothelial ZEB2-loss eventually corrected WD-induced liver hypo-vascularization while ameliorating hepatic damage and steatosis." (PMID 40603966, 2025). "Although endothelial ZEB2 counteracted capillarization during both steatosis and fibrosis7it was only protective against fibrosis, partly through altered communication with hepatic stellate cells." (PMID 40603966, 2025). "Here, we identified endothelial ZEB2 as a multi-factorial instigator of steatosis, thereby down-tuning PPAR(α) signaling, partly through altered communication among LSECs." (PMID 40603966, 2025). "Given our observations that endothelial ZEB2 protects against LSEC capillarization and hepatic fibrosis7we wondered whether ZEB2 would also have a protective role during steatosis." (PMID 40603966, 2025). "Thus, endothelial ZEB2-loss amplifies WD-induced LSEC fat metabolism and capillarization, while decreasing steatosis, in part through altered LSEC-LSEC communication." (PMID 40603966, 2025). "Thus, our model was most suitable to study the role of endothelial ZEB2 in steatosis." (PMID 40603966, 2025). "To investigate a potential protective role against steatosis, the initial MASLD stage, we fed EC-specific Zeb2 knockout (ECZeb2KO) mice a western-type diet (WD)." (PMID 40603966, 2025). "Despite endothelial ZEB2’s multi-factorial effect on steatosis, short- or long-term WD-exposure did not notably alter Zeb2 expression in liver ECs." (PMID 40603966, 2025). "Therefore, we exposed mice to WD and investigated the consequences of EC-specific Zeb2 knockout for LSEC capillarization and steatosis." (PMID 40603966, 2025).
Stickler syndrome (1 paper, 2024). Stickler syndrome is an inherited vitreoretinopathy characterized by the association of ocular signs with more or less complete forms of Pierre-Robin sequence, bone disorders, and sensorineural deafness (10% of cases). "Exome sequencing identified 21 potential pathogenic variants of 13 genes in 20 of 75 (26.7%) probands, including genes for Stickler syndrome (COL11A1 and COL2A1; 6/20), FEVR (FZD4, LRP5, and TSPAN12; 5/20), and others (FBN1, GPR179, ZEB2, PAX6, GPR143, OPN1LW, FRMD7, and CACNA1F; 9/20)." (PMID 38243264, 2024).
T-cell prolymphocytic leukemia (1 paper, 2025). A slow-growing type of leukemia (blood cancer) in which too many lymphocytes are found in the bone marrow and/or blood. "It has been suggested that miR-200c/141 overexpression, which is correlated with the exacerbation of T cell prolymphocytic leukemia, can downregulate ZEB2 and the TGF-β pathway, demonstrating a negative correlation between ZEB2 expression and T cell proliferation." (PMID 40510028, 2025).
teratoma (1 paper, 2017). A non-seminomatous germ cell tumor characterized by the presence of various tissues which correspond to the different germinal layers (endoderm, mesoderm, and ectoderm). "Teratoma formation, using EBs subjected to ND for 12 days showed that Ctrl EBs failed to form teratomas, while Zeb2 KO EBs gave rise to teratomas in 4 weeks." (PMID 27739137, 2017).
thymoma (1 paper, 2015). A neoplasm arising from the epithelial cells of the thymus.
trichorhinophalangeal syndrome type I (1 paper, 2018). An autosomal dominant malformation syndrome caused by mutations in TRPS1 characterized by distinctive craniofacial and skeletal abnormalities. "It has previously been demonstrated that miR-221/222 down-regulate E-cadherin through targeting of the 3′UTR of TRPS1 (trichorhinophalangeal syndrome type 1), a transcriptional repressor that inhibits EMT through repressing ZEB2." (PMID 30591655, 2018).
Ureteral obstruction (1 paper, 2024). Obstruction of the flow of urine through the ureter. "The protein levels of N-Cad, α-SMA, and ZEB2 were increased in the 14-day unilateral ureteral obstruction (UUO 14 days) model and were decreased by the deletion of METTL3." (PMID 39059495, 2024).
urothelial carcinoma (1 paper, 2021). A malignant neoplasm derived from the transitional epithelium of the urinary tract (urinary bladder, ureter, urethra, or renal pelvis). "The results demonstrated low expression of PDE5A, RECK, ZEB2, and CYBRD1 in urothelial carcinoma tissue." (PMID 33987019, 2021). "PDE5A, RECK, ZEB2, and CYBRD1 play essential roles by interacting with other miRNAs and genes in urothelial carcinoma networks which are represented by purple circles." (PMID 33987019, 2021).
tumor (470 papers, 2006 to 2026). "As a central regulator of EMT, ZEB2 is strongly associated with poor clinical prognosis and tumor metastasis and is frequently co-expressed with core mesenchymal markers in various malignancies." (PMID 41194937, 2025). "ZEB1 and ZEB2 are associated with tumor progression and malignancy in human OC by regulating EMT interconversions." (PMID 39796130, 2024). "ZEB2 was shown to promote tumor invasion and metastasis and is associated with poor prognosis in CRC patients." (PMID 35884488, 2022). "Our findings show that ZEB2 is a biomarker of tumour response to chemotherapy and risk of recurrence in CRC patients." (PMID 33931939, 2021). "Dysregulation of ZEB1 and ZEB2 have been involved in tumor progression associated with the development of mesenchymal phenotype, stem-like properties, metastasis, and resistance to therapeutic agents." (PMID 32987716, 2020). "High expression of ZEB2 in cancer tissues defines the reduced ZEB2 expression in the cancer-associated stroma in patients and in murine intestinal organoids, demonstrating a tumour-stromal crosstalk that modulates a niche and EMT activation." (PMID 30783098, 2019). "The ZEB2 is one of the transcription factors associated with transcriptional repression of CDH1 in neoplastic diseases." (PMID 30645591, 2019). "ZEB2 overexpression in tumour-stroma associated cells also correlated with pathological assessment of tumour size, and lymph node metastasis." (PMID 31703358, 2019). "An increased expression of ZEB2 in tumours is correlated with reduced ZEB2 expression in cancer-associated stroma sustaining a tumour-stromal crosstalk and EMT activation." (PMID 31781477, 2019). "In this study, we specifically examined the effect of ZEB2 on tumor cell properties associated with differential gene expression." (PMID 30445998, 2018). "This study contributes to our understanding of the diverse cellular functions of ZEB2 during tumor progression and their underlying mechanisms." (PMID 29416649, 2018). "In contrast, ZEB2 disruption reduced tumour growth and considerably blocked tumour invasion causing the tumours to become encapsulated, with smoother rims, underlining the essential role of ZEB2 in tumour invasion." (PMID 27470974, 2016). "In this study, overexpression of cytoplasmic ZEB2 was associated closely with HCC patient longer survival time as evidenced by univariate analysis in both tumor and peritumoral liver tissues." (PMID 22393452, 2012). "Additionally, high anoikis risk scores were associated with increased mutations frequencies of PTEN, PIK3CA and ZEB2, along with lower tumour mutation burden, microsatellite instability and PD-L1 levels." (PMID 42258564, 2026). "Finally, cell-derived xenograft (CDX) models were generated by subcutaneously implanting pre-treated PC9 or HCC827 cells into BALB/c nude mice to verify the impact of EGFR-TKI resistance and ZEB2 on tumor-associated macrophage (TAM) polarization in vivo." (PMID 40510028, 2025). "Notably, the difference in ZEB2 RNA expression between L6 and the other tumors was highly significant, according to our recent finding that ZEB2 is associated with tumor stemness and EMT in CRC." (PMID 35837106, 2022). "In LSCC, high ZEB2 expression is significantly associated with the advancing in tumor stage, the decrease in differentiation and the shortening of overall survival; down-regulating ZEB2 expression can notably suppress LSCC cell viability, migration, invasion and EMT, and induce the apoptosis." (PMID 35435130, 2022). "However, SMAD4 has also been reported to trigger EMT through the induction of EMT-associated transcriptional factors Snail, ZEB1, and ZEB2, or to function as a tumor promoter." (PMID 36088360, 2022). "ZEB2 also promotes tumor metastasis and is associated with a poor prognosis in patients with CRC." (PMID 35884488, 2022). "Interestingly, our studies showed that ortho-PDX generation was associated to a particularly high expression of ZEB2 in primary tumor cells." (PMID 35837106, 2022).